THBD (thrombomodulin)
Diseases named in the same sentence as THBD in open-access papers (continued):
Sharing a sentence is not in itself a finding about the gene and the disease.
Sepsis (continued). "Conversely, administration of HMGB1-specific neutralizing antibodies or the HMGB1-binding antagonist thrombomodulin can rescue mice and rats from lethal sepsis." (PMID 31092889, 2019). "Increased plasma levels of soluble thrombomodulin have been reported in patients with sepsis and organ dysfunction." (PMID 31121897, 2019). "Several anticoagulants agents, such as antithrombin, recombinant activated protein C (rAPC), recombinant thrombomodulin (rTM), heparin, and tissue factor pathway inhibitor, have been expected and evaluated as adjunctive therapy for the management of sepsis." (PMID 31689983, 2019). "In a Japanese retrospective cohort study to examine the effects of recombinant human thrombomodulin in sepsis-induced DIC patients, 12 patients were assigned to the treatment group and 23 patients were assigned to the control." (PMID 31569648, 2019). "Recombinant human soluble thrombomodulin (rhTM), which has anti-inflammatory effects and mitigates the coagulation cascade, was also developed as a treatment for sepsis." (PMID 30884853, 2019). "Derangement of this thrombomodulin/protein C system in sepsis is well known, and decreased protein C level is recognized as a useful biomarker of severe sepsis." (PMID 31121897, 2019). "Recently, the effect of recombinant thrombomodulin administration in sepsis-induced coagulopathy was evaluated in a randomized controlled study (SCARLET)." (PMID 31416465, 2019). "The present study demonstrates a significant association between prognosis and each specific treatment for sepsis including use of recombinant human soluble thrombomodulin (rhsTM), low-dose steroid therapy, or PMX-DHP." (PMID 30202529, 2018). "Several studies reporting that recombinant human soluble thrombomodulin (rhTM) reduced mortality in sepsis patients." (PMID 30158838, 2018). "A total of 1498 Japanese patients with sepsis and coagulopathy complications who were treated with recombinant thrombomodulin were analysed in this study." (PMID 28963294, 2017). "The Surviving Sepsis Campaign Guidelines 2016 introduced the development of recombinant thrombomodulin, and the European Society of Intensive Care Medicine released comments on this subject." (PMID 28572981, 2017). "Since endothelial dysfunction plays an essential role in the pathogenesis of sepsis, some studies have focused on serum thrombomodulin level as a predictor of the severity of sepsis and mortality in adults." (PMID 28771554, 2017). "The serum thrombomodulin levels on days 1 and 3 were significantly higher in the septic shock group than in the sepsis and severe sepsis groups (p = 0.001 and 0.002, respectively)." (PMID 28771554, 2017). "Anticoagulant therapy for sepsis-associated disseminated intravascular coagulation (DIC) is widely performed in Japan, and antithrombin concentrate and recombinant thrombomodulin are the two most popular agents utilized for this treatment." (PMID 29098447, 2017). "The serum thrombomodulin level was also strongly positively correlated with disease severity of pediatric sepsis." (PMID 28771554, 2017). "In this study, we demonstrated increased serum thrombomodulin levels in children with different sepsis syndromes, sepsis-induced disseminated intravenous coagulopathy and multiple organ failure syndromes." (PMID 28771554, 2017). "Increased serum thrombomodulin levels on days 1 and 3 of the diagnosis of sepsis were found in different pediatric sepsis syndromes." (PMID 28771554, 2017). "It is interesting to note that the effect of hirugen on exosite 1 is similar to that of soluble thrombomodulin, which is currently undergoing clinical trials for the treatment of sepsis and disseminated intravascular coagulation." (PMID 27624125, 2016). "Several anticoagulant therapies, such as recombinant human activated protein C, antithrombin, recombinant tissue factor pathway inhibitor, and recombinant human soluble thrombomodulin (rhTM), have already been evaluated as adjuvant therapy against sepsis." (PMID 27472991, 2016).
Sepsis (continued). "The use of recombinant human soluble thrombomodulin was observed to improve organ dysfunction in patients with sepsis-induced DIC but despite some evidence suggestive of efficacy, it still lacks of a mortality benefit." (PMID 26308340, 2015). "An elevated thrombomodulin serum level is widely regarded as an important biomarker for endothelial dysfunction and has been found to correlate with the severity of sepsis-induced DIC." (PMID 27408725, 2015). "The safety and efficacy of recombinant human soluble thrombomodulin (rhTM) have been demonstrated, with promising evidence suggestive of efficacy for patients with severe sepsis involving coagulopathy in a phase IIb randomized controlled trial." (PMID 25883031, 2015). "The therapeutic benefits of administering recombinant soluble thrombomodulin as a treatment for severe inflammatory disorders such as sepsis-induced DIC have been demonstrated in studies conducted in Japan." (PMID 27408725, 2015). "THBD is a multifunctional immunomodulator and a putative sepsis marker which has recently been suggested to be a component of the LPS-receptor complex CD14/TLR4/MD-2." (PMID 25706641, 2015). "In this respect, generation of APC is dependent on thrombin, yet less dependent on thrombomodulin (which is downregulated in sepsis), thereby conferring some “clot-specificity”." (PMID 25366058, 2014). "In the current study, thrombomodulin levels in patients randomized to placebo began to rise at approximately 36 hours into the study period, indicating sepsis-induced endothelial injury." (PMID 24484547, 2014). "Soluble thrombomodulin is regarded as an accurate marker of endothelial injury and both trauma and sepsis trigger its rapid release into the bloodstream." (PMID 23408987, 2013). "Thrombomodulin (TM), another naturally occurring pathway in the coagulation system, is currently being targeted in the treatment of sepsis." (PMID 23251827, 2012). "A phase II clinical trial is currently underway in the USA to study the efficacy of thrombomodulin for the treatment of sepsis with DIC complications." (PMID 22482044, 2012). "Recently, it has been recognized that endothelial cells play a pivotal role in the pathogenesis of sepsis by releasing tissue factor thrombomodulin and PAI-1." (PMID 17062126, 2006). "During sepsis, however, the expression of thrombomodulin and EPCR on the endothelial cell surface is downregulated, leading to inadequate activation of protein C and thus to inadequate inhibition of thrombin generation." (PMID 16277710, 2005). "Russell noted that genetic variants in thrombomodulin (TM) and endothelial protein C receptor (EPCR) are associated with mortality in sepsis patients and may predict responses to recombinant human TM or activated protein C (APC) therapy." (PMID 41300910, 2025). "In addition to treating sepsis, thrombomodulin has been demonstrated to be active in experimental models of VOD." (PMID 40144213, 2025). "In sepsis, the expression of thrombomodulin, an anticoagulant in the vascular endothelium, is inhibited by inflammatory cytokines, and subsequent excessive production of thrombin results in the formation of multiple microthrombi, which exacerbates sepsis with DIC." (PMID 41164036, 2025). "Some biomarkers that indicate sepsis-related endothelium injury and coagulation dysfunction have been used, such as thrombomodulin (sTM), thrombin–antithrombin complex (TAT), tissue plasminogen activator–inhibitor complex (t-PAIC) and α2-plasmin inhibitor–plasmin complex (PIC)." (PMID 40731775, 2025). "Endothelial dysfunction, and changes related to endothelial-linked proteins, including Soluble thrombomodulin (sTM) and Platelet and Endothelial Cell Adhesion Molecule 1 (PECAM), have been linked to the development of multi-organ failure and death in sepsis patients." (PMID 38245777, 2024).
Sepsis (continued). "Treatment with antithrombin substitution and recombinant thrombomodulin are recommended for sepsis-associated DIC in Japan but are not common in Danish clinical practice." (PMID 39407956, 2024). "During sepsis, immune cells and their inflammatory products activate the endothelium that result in shedding of its ‘fuzz-like’ glycocalyx, indicated by serum elevations in syndecan-1 and soluble-thrombomodulin." (PMID 38811967, 2024). "Suppression of thrombomodulin expression due to sepsis or a systemic inflammatory response may trigger TMA." (PMID 39039520, 2024). "Zhou and colleagues reported that serum soluble thrombomodulin(sTM) and syndecan-1 could be potential biomarkers for the early diagnosis of sepsis." (PMID 37575274, 2023). "In addition, a soluble form of thrombomodulin tested in a clinical trial was shown to improve disseminated intravascular coagulation and sepsis." (PMID 36140236, 2022). "Recently, a SCARLET RCT showed that administration of a recombinant human thrombomodulin (rhTM) did not significantly reduce 28 d all-cause mortality among patients with sepsis-induced coagulopathy compared with placebo." (PMID 35062871, 2022). "We have developed a nomogram that may reliably predict 90-day mortality in patients with sepsis, based on age, international normalized ratio, lactate, and thrombomodulin." (PMID 34722755, 2021). "Furthermore, current state-of-the-art on anti-histone therapy with antibodies, histone-binding proteins (namely recombinant thrombomodulin and activated protein C), and heparin is summarized to propose promising approaches for sepsis treatment." (PMID 33868288, 2021). "Moreover, elevated concentrations of thrombomodulin in blood have been reported in patients with sepsis." (PMID 34263738, 2021). "The treatment effects of thrombomodulin varied across sepsis phenotypes." (PMID 33741010, 2021). "In sepsis, thrombomodulin is a strong predictor of (multi-)organ dysfunction." (PMID 34396466, 2021). "In our previous study reporting the protective effect of recombinant human thrombomodulin (rhTM) in a preterm sepsis mouse model, five LMs were significantly suppressed in the rhTM-treated pups 3 h post-sepsis induction, and an improved survival rate was observed." (PMID 34945120, 2021). "Finally, thrombomodulin has also been proposed as a biomarker for the prediction of mortality in patients with sepsis and septic shock." (PMID 34263738, 2021). "The SCARLET (Sepsis Coagulopathy Asahi Recombinant LE Thrombomodulin) trial that utilized rhsTM to treat sepsis failed to improve the 28-day all-cause mortality rate." (PMID 33679715, 2020). "Human recombinant thrombomodulin (rhTM), an anticoagulant, has anti-inflammatory effects and might be useful for sepsis treatment." (PMID 31941991, 2020). "There were obvious increases in the use of recombinant thrombomodulin for the subpopulations with sepsis and solid cancer: a 320% increase from 12.9% (95% CI 12.4%-13.5%) to 54.6% (95% CI 53.8%-55.3%) and a 450% increase from 9.1% (95% CI 8.5%-9.7%) to 49.7% (95% CI 48.8%-50.6%), respectively." (PMID 33225103, 2020). "Although soluble thrombomodulin is eliminated by renal mechanisms, levels correlate with the severity of organ dysfunction or endothelial damage and have been measured to assess endothelial injury in sepsis." (PMID 31121897, 2019). "Thrombomodulin is released from activated endothelial cells, in the course of sepsis for example." (PMID 31572392, 2019). "However, under pathological conditions such as sepsis and systemic inflammation, endothelial thrombomodulin expression is downregulated and its function impaired." (PMID 31416465, 2019). "However, few pediatric studies have examined the role of serum thrombomodulin as a biomarker to predict the clinical course of different pediatric sepsis syndromes, sepsis-induced DIC, MODS and mortality." (PMID 28771554, 2017).
Sepsis (continued). "Serum thrombomodulin levels may also be used as an early predictor of mortality in pediatric patients with sepsis." (PMID 28771554, 2017). "Measurements of serum thrombomodulin may help to early recognize the development of septic shock, sepsis-induced DIC and MODS to allow for more appropriate therapeutic strategies." (PMID 28771554, 2017). "However, a fundamental concept is that both antithrombin and thrombomodulin activities are significantly reduced and anticoagulatory function is disrupted during sepsis." (PMID 29098447, 2017). "Therefore, measurements of serum thrombomodulin still help to early recognize the development of septic shock, sepsis-induced DIC and MODS." (PMID 28771554, 2017). "We examined the hypothesis that recombinant human soluble thrombomodulin (rhTM) is effective in the treatment of patients with septic shock with sepsis-induced DIC after laparotomy for intestinal perforation." (PMID 25767801, 2015). "Because both AT and thrombomodulin activities are known to decrease significantly during severe sepsis and their mechanisms of action are independent, a combination therapy could potentially be beneficial." (PMID 25220851, 2014). "We have previously reported that experimental endotoxemia in healthy volunteers receiving a 4-h 0.5 ng/kg/h infusion of E. coli lipopolysaccharide did not result in significant changes of circulating levels of catecholamines, syndecan-1 or soluble thrombomodulin contrary to patients with sepsis." (PMID 25505423, 2014). "Recombinant thrombomodulin (rTM), which binds to thrombin in vivo and controls the ability to activate platelet function and fibrin formation, has been approved for DIC associated with sepsis in Japan." (PMID 25520829, 2014). "Recombinant human soluble thrombomodulin may improve sepsis-induced DIC diagnosed according to the JAAM criteria without an increased bleeding risk." (PMID 23414216, 2013). "Recombinant human soluble thrombomodulin administration may improve sepsis-induced DIC diagnosed according to the JAAM criteria without an increased bleeding risk." (PMID 23414216, 2013). "In sepsis, both the coagulation and the fibrinolytic system may be affected, as indicated by decreased activation of thrombomodulin and protein C as well as reduction of anti-fibrinolysis and enhancement of plasminogen activator inhibitor (PAI)-1 expression." (PMID 17062126, 2006). "Among other immune-modulating treatments, recombinant human thrombomodulin (rhTM) has anti-inflammatory and anticoagulation activities, and it has been suggested as an adjunct therapy for patients with sepsis, particularly those with sepsis-induced coagulopathy." (PMID 41590521, 2026). "Recombinant thrombomodulin was associated with a trend in reduced mortality in sepsis with coagulopathy with no increased risk of bleeding, although the difference was not statistically significant and the required information size for any declarative judgement insufficient." (PMID 31689983, 2019). "Therefore, the serum thrombomodulin level in patients with sepsis may be used as a biomarker to monitor the resolution or aggravation of DIC and MODS." (PMID 28771554, 2017). "Therefore, it is difficult to confirm the pathophysiological role of thrombomodulin in sepsis." (PMID 28771554, 2017). "The efficacy of anticoagulants depends on the severity of the sepsis, and the efficacy of recombinant thrombomodulin was revealed in a population in which the post-treatment mortality was 20 % or more, but it might not be efficient in a population with a mortality rate of less than 20 %." (PMID 27629997, 2016). "It is possible that other reported prothrombotic effects of sCD40L, such as reduced thrombomodulin expression and binding to the glycoprotein IIb/IIIa platelet receptor could lead to vascular thrombosis and, finally, death in patients with severe sepsis." (PMID 21406105, 2011).
Sepsis (continued). "For sepsis-induced DIC, the anticoagulant substance recombinant human soluble thrombomodulin (rTM) has been developed." (PMID 41164036, 2025). "In the SCARLET trial, 800 patients with severe sepsis (according to the sepsis-2 definition) and SAC were randomized; half of the patients received recombinant soluble thrombomodulin and the other half received a placebo." (PMID 40565967, 2025). "Current sepsis therapeutic strategies targeting the fibrinolytic system focus on thrombolytic drugs (such as Antithrombin‐III and Recombinant human soluble thrombomodulin (rhTM)) and antifibrinolytic drugs (such as tranexamic acid and aminocaproic acid)." (PMID 41219162, 2025). "Plasma samples from all sepsis cases also displayed an increase in vWF concentration as well as differences in the concentrations of factors VII, V, prothrombin, and thrombomodulin." (PMID 36829233, 2023). "Specifically, the model rats were divided into three groups: (i) the sham group as a control group; (ii) the cecum ligation and puncture (CLP) group with sepsis; and (iii) the CLP+thrombomodulin (TM) group with sepsis and the application of TM alfa therapy." (PMID 36366167, 2022). "Several biomarkers also had a predictive value for sepsis mortality, such as first urine liver-type fatty acid binding protein (L-FABP), natural killer (NK) cell concentration, and serum thrombomodulin." (PMID 36908280, 2022). "Thrombomodulin also has anti-inflammatory effects, and recombinant thrombomodulin is highly effective in cases of DIC complicated by hematopoietic tumors and sepsis." (PMID 35163216, 2022). "In clinical applications, thrombomodulin is also useful in HMGB1-related diseases and conditions such as sepsis because of its anti-HMGB1 properties." (PMID 24244627, 2013). "In the SCARLET trial soluble thrombomodulin did not reduce mortality in unselected sepsis patient (27% vs. 29%, n = 800)." (PMID 38807151, 2024). "In fact, when measuring pediatric sepsis patients on day 1 and day 3 of admission, non-survivors likely have higher levels of serum thrombomodulin compared to survivors." (PMID 36793336, 2023). "In conclusion, anticoagulant therapy, namely, the administration of antithrombin, recombinant human thrombomodulin, or their combination, showed a beneficial effect on hospital mortality according to a higher JAAM DIC score in patients aged 60 to 70 years with sepsis." (PMID 35660774, 2022). "In the pathophysiology of sepsis, THBD promotor may influence the thrombomodulin-guided APC function and limit endothelial cell damage." (PMID 35083232, 2021). "A recent randomised trial showed that recombinant thrombomodulin did not benefit patients who had sepsis with coagulopathy and organ dysfunction." (PMID 33741010, 2021). "The effect of recombinant thrombomodulin administration in sepsis-induced coagulopathy in the SCARLET study was not statistically significant." (PMID 33632246, 2021). "In this article, therapeutic agents used for immunothrombosis, such as activated protein C and thrombomodulin, failed to prove effective for sepsis in clinical trials." (PMID 33679715, 2020). "According to several randomized controlled trials and meta-analyses, antithrombin and recombinant thrombomodulin had no therapeutic benefit in the treatment of sepsis." (PMID 32082581, 2020). "In contrast to the situation in Japan, the international guidelines for sepsis do not recommend the use of antithrombin, and recombinant thrombomodulin is still not available outside Japan." (PMID 29098447, 2017). "Serum thrombomodulin levels may also be used to monitor the evolution of DIC and MODS in patients with sepsis." (PMID 28771554, 2017). "Clinical trials have investigated the use of recombinant soluble thrombomodulin therapy in sepsis, DIC, and ARDS, though no conclusive pediatric data are available as of yet." (PMID 26652251, 2015).